NFIC (nuclear factor I C)
Diseases named in the same sentence as NFIC in open-access papers (continued):
Sharing a sentence is not in itself a finding about the gene and the disease.
esophageal squamous cell carcinoma (1 paper, 2021). Esophageal squamous cell carcinoma (ESCC) is a type of esophageal carcinoma (EC) that can affect any part of the esophagus, but is usually located in the upper or middle third. "An existing study identified the ability of NFIC to serve as a crucial transcription factor in esophageal squamous cell cancer." (PMID 34666602, 2021). "Previously, NFIC has been demonstrated to play a regulatory role in esophageal squamous cell cancer." (PMID 34666602, 2021). "An existing research determined the inhibitory role of NFIC in the invasion, migration, or metastasis via suppression of EMT in esophageal squamous cell cancer." (PMID 34666602, 2021).
head and neck cancer (1 paper, 2020). A primary or metastatic malignant neoplasm affecting the head and neck. "Decreased expression levels of NFIA, NFIB and NFIC were associated with poor overall survival (OS) in head and neck cancer." (PMID 32219034, 2020).
infiltrating bladder urothelial carcinoma (1 paper, 2020). An invasive transitional cell carcinoma that arises from the urinary bladder urothelium. "NFIA, NFIB and NFIC expressions were decreased in both superficial bladder cancer and infiltrating bladder urothelial carcinoma compared with normal tissues in Lee, Sanchez-Carbayo2 and Blaveri2’s studies." (PMID 32219034, 2020).
kidney chromophobe cell carcinoma (1 paper, 2020). "In addition, expression of NFIA and NFIB was downregulated in kidney chromophobe cell carcinoma, whereas expression of NFIC and NFIX was upregulated." (PMID 32219034, 2020). "Contrary to kidney chromophobe cell carcinoma, expression of NFIA and NFIB was upregulated in kidney papillary cell carcinoma and expression of NFIC and NFIX was reduced." (PMID 32219034, 2020).
liver cancer (1 paper, 2020). An epithelial or non-epithelial malignant neoplasm that arises from the liver. "Besides, decreased NFIC expression level was associated with poor PFS and NFIB expression was uncorrelated with OS in liver cancer patients." (PMID 32219034, 2020).
lung adenocarcinoma (1 paper, 2020). A carcinoma that arises from the lung and is characterized by the presence of malignant glandular epithelial cells. "Two comparisons with Bhattacharjee’s database indicated the NFIC mRNA level was reduced in lung adenocarcinoma and SCLC." (PMID 32219034, 2020).
pancreatic ductal adenocarcinoma (1 paper, 2023). An infiltrating adenocarcinoma that arises from the epithelial cells of the pancreas. "NFIC expression is down-regulated in mouse and human pancreatic ductal adenocarcinoma." (PMID 37353485, 2023).
pancreatitis (1 paper, 2023). Inflammation of the pancreas. "NFIC is down-regulated during caerulein pancreatitis and is required for recovery after damage." (PMID 37353485, 2023).
psoriasis (1 paper, 2022). An autoimmune condition characterized by red, well-delineated plaques with silvery scales that are usually on the extensor surfaces and scalp. "NFIC, NFYA, POU2F2, FOXA1 and SRF were discovered to be significant in psoriasis in our study after a gene-transcription factor regulatory network and several relevant transcription factors were evaluated." (PMID 36499614, 2022).
pulmonary arterial hypertension (1 paper, 2023). Pulmonary arterial hypertension (PAH) is a group of diseases characterized by mean pulmonary artery pressure >20 mmHg and elevated pulmonary arterial resistance leading to right heart failure. "This approach was used in a paper from this year that shows significant upregulation of SOCS3, ITGAL, NFIC, NCOR2, and PGK1 mRNA (qRT-PCR) in peripheral blood mononuclear cells from pulmonary arterial hypertension (PAH) patients compared to healthy controls (p ≤ 0.05)." (PMID 37762023, 2023).
renal tumors (1 paper, 2022). "In silico analysis showed that tRF-5b can regulate the activity of the NFIC, GNAO1 and HIPK2 proteins, which are associated with renal tumors." (PMID 35409004, 2022).
rheumatoid arthritis (1 paper, 2023). A chronic, systemic autoimmune disorder characterized by inflammation in the synovial membranes and articular surfaces. "In mice, NFIC regulates the expression of PTEN/SENP8 and inhibits rheumatoid arthritis-induced inflammation." (PMID 37244954, 2023).
schizophrenia (1 paper, 2022). A major psychotic disorder characterized by abnormalities in the perception or expression of reality. "Genetic risk factors that overlap with TF-binding sites for USF1, NFIC, and POLR2A have been identified in relation to schizophrenia and MDD." (PMID 36386175, 2022).
serous ovarian cancer (1 paper, 2022). "Accordingly, overexpression of some acting on genes like FOSL2, NFIB, NFIC, and PROCR, which are associated with proliferation and metastasis, predicts poor prognosis in high-grade serous ovarian cancer." (PMID 35935940, 2022).
type 2 diabetes (1 paper, 2017). "These signaling pathways contained the significant gene regulatory network of transcript factors families for type 2 diabetes including SP1, NFIC, ZFP161, and FOS, JUND, JUNB." (PMID 28179884, 2017).
tumor (27 papers, 2008 to 2025). "Dysregulation of NFIC was recently reported to be involved in cell proliferation, migration, tumour invasion." (PMID 35293050, 2022). "Our future studies will investigate the mechanism of NFIC in ESCA cells with in vivo TE-1 tumor model establishment to validate our findings." (PMID 34666602, 2021). "One promising strategy involves the use of bromodomain-containing protein 4 (BRD4) inhibitors or bromodomain and extraterminal domain inhibitors (BETis) to downregulate NFIC expression, potentially inhibiting tumor progression and increasing the efficacy of existing treatments." (PMID 41194225, 2025). "Targeting NFIC presents an opportunity to disrupt the metabolic pathways that sustain tumor growth." (PMID 41194225, 2025). "We found that most of the genes associated with cell survival were found to be upregulated in NFIC overexpressing as compared to control monocytes and were sub-divided into three major functional nodes of cell survival, colony formation and cell viability of tumor cells." (PMID 36572750, 2023). "Moreover, METTL3 inhibition could increase the NFIC transcriptional level to repress tumor growth and lung metastasis in vivo." (PMID 34666602, 2021). "Among these, the top three TFs—NFIC, HOXB2, and BCL6—demonstrated notably high expression in tumor cells." (PMID 40190189, 2025). "Our results demonstrated that METTL3 and miR-20a-5p were downregulated while the NFIC transcriptional level was upregulated in the tumors (P < 0.001), and METTL3 inhibition had suppressed tumor growth (P < 0.001)." (PMID 34666602, 2021). "Among the potential target genes of miRNA-328-5p, the DAB2IP, NFIC, IL-27, and HIC1 genes were tumor suppressors." (PMID 31776329, 2019). "Similarly, SLC12A1 is regulated by NFIC, GATA2 and FOXC1, ensures ionic balance and cellular volume, thereby supporting tumor cell survival and aggressive behavior." (PMID 39348357, 2024). "In ccRCC, NFIC and GATA2 regulate ALDH6A1 expression, enhancing its capacity to manage oxidative stress and detoxify harmful metabolites, which is crucial in the tumor environment." (PMID 39348357, 2024). "Remarkably, we detected a significantly more enrichment of NFIC within METTL3 regulatory region in non-tumor pancreatic tissues from smokers than that from nonsmokers." (PMID 31015415, 2019). "For example, NFIC was not considered because it was enriched at #4 in the tumor-specific analysis but also at #11 in the developmentally shared analysis." (PMID 30275445, 2018).
cancer (25 papers, 2014 to 2025). A tumor composed of atypical neoplastic, often pleomorphic cells that invade other tissues. "Finally, NFIC, a member of the nuclear factor I family, has been implicated in various types of cancer." (PMID 40722679, 2025). "However, a differential effect on IFN-ɣ-mediated PD-L1 up-regulation based on allele-specificity of rs822336 was detected in cancer cells silenced for C/EBPβ and/or NFIC." (PMID 38528526, 2024). "TP has been shown to confer survival advantage to cancer cells under nutrient deficient conditions and may possibly explain NFIC-HSPCs growth in cytokine-free cultures." (PMID 36572750, 2023). "We identified significant downregulation of several metabolic pathways related to hepatic functionality, PPAR signaling, and drug metabolism for NFIB, NFIC, and NFIX, whereas pathways associated with cancer biology were significantly induced." (PMID 41106572, 2025). "Although dysregulation of NFIC has been reported in different cancers this study to the best of our knowledge is the first attempt to mechanistically explores its role in AML." (PMID 36572750, 2023). "The identified TFs, such as FOXC1, FOXL1, POU2F2, NFIC, NFkB1, MEF2A, GATA2, and E2F1, are mainly associated with different types of cancers and congenital disorders." (PMID 37026010, 2023). "NFIC protein is a part of the NFI family, which is primarily downregulated in most types of cancers and associated with tumor suppressors." (PMID 34666602, 2021). "Next, we detected the expression patterns of miR-20a-5p and NFIC in 60 pairs of cancer tissues and normal paracancerous tissues, followed by Pearson correlation analysis of miR-20a-5p and NFIC." (PMID 34666602, 2021). "NFIA, NFIB and NFIC expression levels were reduced in cancer tissues evaluated using mRNA HiSeq expression data from the TCGA database." (PMID 32219034, 2020). "Interestingly, the NFIC transcription factor regulates osteoblast differentiation, and can promote or suppress the development of various cancers via epigenetic changes." (PMID 33603167, 2021). "Esophageal cancer-related gene-4 could positively regulate the protein levels of NFIC in BCa cells." (PMID 32922434, 2020). "As a result, in cancer cells carrying C/C genotype the significant higher differential increase in PD-L1 induction is likely to reflect the unbalanced competitive binding induced by IFN-ɣ on C/EBPβ and NFIC." (PMID 38528526, 2024). "We found that MSC, NFIA, NFIC and TCF21 were significantly effective regulons for fibroblasts in more than three cancers, indicating that they might be crucial in driving changes in cell state." (PMID 36772945, 2023).
NFIC also shares sentences with these, for which no sentence is quoted: breast invasive carcinoma (2 papers); digestive system carcinoma (2); infection (2); lymphoma (2); uveal melanoma (2); acute erythroid leukemia (1); aneurysm (1); astrocytoma (1); bladder urothelial carcinoma (1); brain tumor (1); breast tumors (1); cholestasis (1); colorectal cancer (1); diabetic retinopathy (1); ependymoma (1); gestational diabetes (1); head and neck squamous cell carcinoma (1); hepatocellular carcinoma (1); HIV-1 infection (1); Intellectual disability (1); ischemic cardiomyopathy (1); ischemic stroke (1); kidney cancer (1); lobular breast carcinoma (1); lupus (1); malignant glioma (1); mesothelioma (1); metabolic disorders (1); neuroblastoma (1); neurological diseases (1).
A further 8 diseases each share a sentence with NFIC in 1 paper.